CPZ (carboxypeptidase Z)
Description:
Specifically cleaves substrates and peptides with C-terminal basic amino acids, especially those containing C-terminal Arg residues. Probably modulates the Wnt signaling pathway, by cleaving some undefined protein. May play a role in cleavage during prohormone processing.
Tractability: Antibody: UniProt places it where antibodies can reach, with high confidence; UniProt predicts a signal peptide or a membrane-spanning region; its Gene Ontology location is reachable by antibodies, with medium confidence; the Human Protein Atlas places it where antibodies can reach.
Gene: Protein-coding gene on chromosome 4 (8,592,660 to 8,619,761, forward strand). Ensembl gene ENSG00000109625.
Subcellular location: Secreted, extracellular space; Secreted, extracellular space, extracellular matrix
Subcellular location (Human Protein Atlas): Plasma membrane; Predicted to be secreted
Gene Ontology:
Molecular function: carboxypeptidase activity; metallocarboxypeptidase activity; zinc ion binding
Biological process: peptide metabolic process; protein processing; proteolysis
Cellular component: extracellular matrix; extracellular region
Genetic constraint (gnomAD): Loss-of-function variants: 103 observed, 57.6 expected, observed/expected ratio (o/e) 1.79, 90% interval 1.51 to 1.97. The synonymous counts are far from expectation, so gnomAD's model fits this gene poorly and the ratio says little. Missense variants: 1,453 observed, 902.62 expected, observed/expected ratio (o/e) 1.61, 90% interval 1.54 to 1.68. Synonymous variants: 545 observed, 365.22 expected, observed/expected ratio (o/e) 1.49, 90% interval 1.39 to 1.6.
Homologues: Orthologues: chimpanzee CPZ (99% identical), macaque CPZ (97% identical), pig CPZ (87% identical), dog CPZ (83% identical), mouse Cpz (82% identical), rat Cpz (81% identical), guinea pig CPZ (78% identical), tropical clawed frog cpz (60% identical), zebrafish cpz (54% identical). Paralogues in human: CPD (35% identical), CPE (34% identical), CPXM1 (33% identical), AEBP1 (32% identical), CPN1 (32% identical), CPXM2 (31% identical), CPM (25% identical).
Diseases named in the same sentence as CPZ in open-access papers:
CPZ is named in the same sentence as 33 diseases in open-access papers, as found by Europe PMC text mining. Sharing a sentence is not in itself a finding about the gene and the disease. The quoted sentences say what the papers report.
gastric cancer (3 papers, 2023 to 2025). A primary or metastatic malignant neoplasm involving the stomach. "After identifying these prognostic genes, including CPZ, CTHRC1, DKK1, EGF, and GPC3, we will explore their specific impact on gastric cancer progression, as well as the molecular mechanisms underlying it, particularly the CPZ." (PMID 40296906, 2025). "In view of the relationship between the Wnt signaling pathway and gastric cancer, we identified the prognostic five genes signatures related to the Wnt pathway in this study, including CPZ, CTHRC1, DKK1, EGF, and GPC." (PMID 40296906, 2025). "Given CPZ’s significant prognostic impact, we confirmed its overexpression in gastric cancer tissues using qPCR on our clinical patient samples." (PMID 40296906, 2025). "Among these five signature genes, CPZ has been less studied in gastric cancer, prompting us to analyze its prognostic impact." (PMID 40296906, 2025). "This study experimentally verified the levels of DNA repair-relevant genes, with higher levels of PAPPA2, MPO, MAGEA11, DEPP1, CPZ, and COLEC12 and lower level of CYTL1 in gastric cancer cells versus controls." (PMID 37124627, 2023). "In contrast to gastric mucosa epithelial cell line GES-1, transcriptional levels of PAPPA2, MPO, MAGEA11, DEPP1, CPZ, and COLEC12 were higher in gastric cancer cell lines HGC-27, MKN-28 and AGS, with lower transcriptional level of CYTL1." (PMID 37124627, 2023). "Higher levels of PAPPA2, MPO, MAGEA11, DEPP1, CPZ, and COLEC12 and lower level of CYTL1 were proven in gastric cancer cells versus controls." (PMID 37124627, 2023).
neuroblastoma (3 papers, 2017 to 2025). Neuroblastoma (NB) is the most common solid, extracranial childhood tumor. "Taken together, these data suggest that rs3796727 genotype may be associated with decreased methylation and increased CPZ expression; further study is necessary to confirm this role for rs3796727 in neuroblastoma directly." (PMID 28545128, 2017). "Furthermore, significantly reduced methylation of the 5’ UTR of CPZ on chromosome 4p16 and increased CPZ gene expression in neuroblastoma patients may increase susceptibility to neuroblastoma." (PMID 41001032, 2025). "Taken together, we show that common DNA variants within CPZ at 4p16 and upstream of MLF1 at 3q25 influence neuroblastoma susceptibility and MLF1 likely plays an important role in neuroblastoma tumorigenesis." (PMID 28545128, 2017). "Ongoing studies will further elucidate the role of both CPZ and MLF1 in neuroblastoma tumorigenesis." (PMID 28545128, 2017).
viral infection (2 papers, 2025). "To determine whether macropinocytosis is involved in RGNNV entry into hMMES1 cells, we used a panel of compounds to treat the cells prior to viral infection, including EIPA (macropinocytosis inhibitor), Rottlerin (macropinocytosis inhibitor), CPZ (CME inhibitor), and Nystatin (caveolin inhibitor)." (PMID 40560751, 2025).
adenoma (1 paper, 2025). A neoplasm arising from the epithelium. "The CPZ gene produces significant immunohistochemical (IHC) staining in the tissues of adrenocorticotropic hormone-synthesizing suprarenal cortical cell adenomas, adenomas of growth hormone (GH)-producing GH cells, and adenomas of prolactin-producing lactation cells." (PMID 41001032, 2025).
Anxiety (1 paper, 2018). Intense feelings of nervousness, tension, or panic often arise in response to interpersonal stresses. "There are significances about the interaction of response, trait and state anxiety over right parietal (i.e., P1/P4) and centroparietal (i.e., CP1/CPZ/CP2/CP4/CP6)." (PMID 30385790, 2018). "The interactions of valence, response and state anxiety were significant over right parietal (i.e., P4) and centroparietal (i.e., CP1/CPZ/CP2/CP4/CP6)." (PMID 30385790, 2018).
breast carcinoma (1 paper, 2025). "The analysis identified a significant positive association connecting CPZ expression and CAF infiltration in GC, cholangiocarcinoma (CHOL), and breast cancer (BC)." (PMID 41001032, 2025).
catalepsy (1 paper, 2017). A nervous system disorder characterized by diminished responsiveness and consciousness, and rigidity of the body. "However, since SNE causes catalepsy (at high doses) just as much as HAL and CPZ, the doses of these orthodox drugs must be reduced if combined with SNE to prevent exaggerated extrapyramidal motor side effects while possibly enhancing the therapeutic outcome." (PMID 28784133, 2017).
cholestasis (1 paper, 2017). Impairment of the bile flow caused by obstruction within the liver, or outside the liver in the bile duct system. "CPZ, which is known to induce mixed cholestasis/hepatocellular liver injury, showed both an early and late liver signal." (PMID 28115551, 2017).
coagulation disorders (1 paper, 2024). "In the first study of its kind, we reported that the combination of CPZ/SAM and carbapenem might increase the risk for coagulation disorders." (PMID 38997770, 2024).
demyelination (1 paper, 2015). "In our study, PDGFRα-positive and NG2-positive OPCs increased in the cortex of mice subjected to CPZ-induced demyelination." (PMID 25815032, 2015).
depression (1 paper, 2019). "The results indicate that CPZ exposure for 5 weeks may not lead to an early depression-like behavior." (PMID 31024304, 2019).
glaucoma (1 paper, 2025). Increased pressure in the eyeball due to obstruction of the outflow of aqueous humor. "CPZ, a tier 3 target gene for glaucoma with tier 3B evidence for druggability, also exhibited a protective role in glaucoma, associated with IOP reduction according to the glaucoma endophenotype analysis." (PMID 40635100, 2025). "Additionally, CPZ and PXDN demonstrated protective and risk-associated roles in glaucoma, respectively, supported by tier 3 evidence." (PMID 40635100, 2025). "By using a comprehensive analysis pipeline, we identified five potential therapeutic targets for glaucoma: two tier 1 genes (CPXM1 and FLT4), one tier 2 gene (INSR), and two tier 3 genes (CPZ and PXDN)." (PMID 40635100, 2025). "First, we could not fully explore all druggable genes for glaucoma due to the limited availability of pQTLs and specific genes in the eQTL dataset, such as CPZ, which restricted our ability to prioritise gene tiers." (PMID 40635100, 2025).
glioblastoma (1 paper, 2021). The most malignant astrocytic tumor (WHO grade IV). "Our results found that Hg from the amalgam in the LCu or HCu groups induced cell death in human DBTRG glioblastoma cells, regardless of time, although the cell viability in these groups was increased by Se and/or CpZ." (PMID 33624687, 2021).
glioma (1 paper, 2022). A benign or malignant brain and spinal cord tumor that arises from glial cells (astrocytes, oligodendrocytes, ependymal cells). "CPZ triggers autophagy in the PTEN-null U-87 MG glioma cell line by inhibiting the AKT/mTOR axis, thus driving them toward a non-apoptotic cell death." (PMID 35053377, 2022). "RIS and CPZ decrease the level of expression of PCNT in C6 glioma cells, whereas HAL does not." (PMID 35053377, 2022).
hepatitis (1 paper, 2015). Inflammation of the liver. "We showed that the strongly increased recruitment of transferred CD4+ T cells into the inflamed liver of Con A-treated mice was abolished after administration of CPZ during hepatitis whereas the clathrin inhibitor did not influence CD4+ T-cell migration to the healthy liver." (PMID 26052942, 2015). "We excluded inhibitory effects of CPZ on T-cell activation in vivo and another study also showed that CPZ did not affect inflammatory cytokine production during Con A-induced hepatitis which could be possible reasons for the reduced hepatic infiltration of effector CD4+ T cells." (PMID 26052942, 2015).
Hypertension (1 paper, 2023). The presence of chronic increased pressure in the systemic arterial system. "Also, CPZ injection itself did not affect the development of hypertension." (PMID 37384285, 2023).
Hypoalbuminemia (1 paper, 2024). The concentration of albumin in the blood circulation is below the lower limit of normal. "CPZ is a highly protein-bound drug with a binding rate of up to 90%, it is excreted more quickly into the intestines through the biliary tract in patients with hypoalbuminemia." (PMID 39830359, 2024).
lipidosis (1 paper, 2012). "CPZ has sometimes been considered to be a class 2 agent because of its potential to induce LE/L lamellar body formation or “lipidosis”." (PMID 22276143, 2012).
liver inflammation (1 paper, 2015). "We also tested the effect of CPZ on chemokine-dependent T-cell infiltration during liver inflammation." (PMID 26052942, 2015). "Despite potential other effects of CPZ on lymphocyte function, our in vitro data suggested CPZ as a suitable model substance for this first study on the impact of clathrin inhibition on the course of liver inflammation." (PMID 26052942, 2015). "Strikingly, despite liver inflammation, migration of CD4+ T cells into the liver was significantly reduced if mice received CPZ in addition to Con A. CPZ itself did not influence hepatic migration of transferred CD4+ T cells in healthy mice." (PMID 26052942, 2015).
lymph node metastasis (1 paper, 2025). "The analysis indicated that the N stage had the highest overall HR among the significant correlates, which suggested that the expression of CPZ was linked to the degree of lymph node metastasis, which affects the prognosis of patients with GC." (PMID 41001032, 2025).
malignant glioma (1 paper, 2021). A grade III or grade IV glioma arising from the central nervous system. "Among these, CPZ has been shown effective in hindering key biological features of cancer cells in vitro, also in the case of malignant gliomas." (PMID 33718225, 2021). "Several reports claim for CPZ the ability of protecting from apoptosis in either normal neural cells exposed to toxic stimuli or malignant glioma cells." (PMID 33718225, 2021).
ovarian carcinoma (1 paper, 2021). A malignant neoplasm originating from the surface ovarian epithelium. "CPZ(Carboxypeptidase Z) expression was significantly lower ovarian cancers and may be relevant to the biology of high-grade serous ovarian cancers." (PMID 33790307, 2021).
schizophrenia (1 paper, 2020). A major psychotic disorder characterized by abnormalities in the perception or expression of reality. "On average, CPZ in patients with schizophrenia (370.6 ± 462.4 mg day−1, mean ± s.d)." (PMID 32843635, 2020).
cancer (7 papers, 2012 to 2025). A tumor composed of atypical neoplastic, often pleomorphic cells that invade other tissues. "We used TIMER2.0 to investigate the link connecting the infiltration levels of cancer-associated fibroblasts (CAFs) and CPZ gene expression across TCGA cancer datasets." (PMID 41001032, 2025). "The TIMER2.0 analysis of pan-cancer identified significant CPZ overexpression in tissues from GC compared to normal tissues." (PMID 41001032, 2025). "The relationship between CPZ gene expression and drugs related to cancer treatment was investigated by dividing the cases into groups based on CPZ expression (cut-off value: 50%)." (PMID 41001032, 2025). "Differential CPZ expression in cancer and paracancerous tissues was verified using immunohistochemistry (IHC) and quantitative PCR (qPCR)." (PMID 41001032, 2025). "CPZ gene expression in pan-cancer analysis was conducted using the Tumor Immune Estimation Resource (TIMER2.0) database." (PMID 41001032, 2025). "We succeeded in finding relatively new co-expressed genes, such as TIMELESS, IDUA, CPZ, MGC27165, C10orf56 and so on that were found to be associated with BC or other cancers until this decade." (PMID 33790307, 2021). "Here we confirm the ability of CPZ in restraining key cancer cell features, adding further information concerning the effect of the drug on six human GBM cell lines, either anchorage-dependent or patient-derived neurospheres." (PMID 33718225, 2021). "Furthermore, several reports show that CPZ can inhibit cancer cell growth through several mechanisms." (PMID 33718225, 2021). "CPZ participates in adaptive immune responses and affects the TME, has excellent immunomodulatory capabilities, and promotes cancer development." (PMID 41001032, 2025). "Colony- and sphere-forming ability assays demonstrate that CPZ cooperated with TMZ in reducing GBM cell cloning efficiency, a distinctive signature of malignancy in cancer cells." (PMID 33718225, 2021). "In addition, CPZ was able to downregulate the expression of OCT 3/4, SOX2, NANOG, Nestin, OLIG2 and ALDH1A3, universal cancer stem cells genes for GBM." (PMID 33718225, 2021).
infection (5 papers, 2009 to 2025). The state of being infected such as from the introduction of a foreign agent such as serum, vaccine, antigenic substance or organism. "The results indicated that EIPA, Rottlerin, and CPZ significantly inhibited RGNNV infection compared to the dimethyl sulfoxide (DMSO) control, whereas Nystatin had no obvious effect, indicating RGNNV enters hMMES1 cells via macropinocytosis and CME pathways." (PMID 40560751, 2025). "In most cases, sulbactam exerted the main effect against infection by Ab in the complex CPZ/SUL, which was similar to the literature reports." (PMID 35625347, 2022). "Actually, treatment with CPZ did not inhibit ANDV infection, but rather enhanced ANDV infection." (PMID 27780263, 2016).
tumor (5 papers, 2017 to 2025). "The link between the expression of CPZ and the infiltration of fibroblasts and immune cells was investigated in depth, its relationship with immune checkpoints and tumor mutational burden (TMB) was examined, and drug sensitivity was analyzed." (PMID 41001032, 2025). "Our exploration of the link between CPZ expression and the sensitivity to numerous anti-tumor drugs revealed that high CPZ expression is associated with reduced sensitivity to some first-line chemotherapeutic drugs, such as oxaliplatin, cisplatin, and docetaxel." (PMID 41001032, 2025). "Elevated CPZ expression in GC tissues affects patient survival prognosis and can increase immune cell infiltration, affecting the tumor microenvironment." (PMID 41001032, 2025). "As bioinformatics analysis results are not always reliable, we collected samples from clinical patients with GC and confirmed statistically significant increased CPZ expression in their tumor tissues through IHC and RT-qPCR." (PMID 41001032, 2025). "In GC tissue, in addition to the expression of fibroblasts, SERPINF1 was also expressed in tumor cells, suggesting a similar expression pattern of CPZ." (PMID 40296906, 2025). "We also analyzed the relationship between the expression of CPZ and the prognosis and characteristics of the tumor." (PMID 41001032, 2025). "CPZ expression influenced immune cell and fibroblast infiltration in the GC tumor microenvironment." (PMID 41001032, 2025). "However, CPZ may influence tumor initiation and thus require assessment of precursor cells from the developing sympathetic nervous system." (PMID 28545128, 2017). "The analysis revealed that the group with high CPZ expression had significantly higher stromal, immune, and ESTIMATE scores than the group with low expression, indicating a high immune and stromal cell content and low tumor purity." (PMID 41001032, 2025). "Furthermore, CPZ without capsaicin also decreases cell proliferation and tumour size, and even promotes the effect of chemo and radiotherapy." (PMID 33609025, 2021). "These authors also carried out an in vivo experiment with mice, and they found that CPZ treated HSC3 tumours did not enlarge as much as control group, and dramatically shrank in size, similar to SCC25 tumours, which displayed a marked reduction in tumour volume following treatment with CPZ (50.5%)." (PMID 33609025, 2021).
psychiatric disorder (1 paper, 2021). A disorder characterized by behavioral and/or psychological abnormalities, often accompanied by physical symptoms. "CPZ is the progenitor of the DRD2 inhibitors phenothiazines and is used since the 50s in the therapy of several psychiatric disorders, e.g. acute and chronic psychosis, and provides relief from severe vomiting and untreatable hiccups." (PMID 33718225, 2021).
CPZ also shares sentences with these, for which no sentence is quoted: anaphylaxis (1 paper); cholangiocarcinoma (1); colon cancer (1); Hyperglycemia (1); migraine (1); Stroke (1).